INS (insulin)
Diseases named in the same sentence as INS in open-access papers (continued):
Sharing a sentence is not in itself a finding about the gene and the disease.
Hepatic steatosis (continued). "5αR1−/− (but not 5αR2−/−) mice fed an ALIOS diet developed greater hepatic steatosis than WT mice, and hepatic mRNA expression of genes involved in insulin signaling was decreased." (PMID 24080367, 2013). "Previous characterizations of these subjects showed that hepatic steatosis was not accompanied with hepatic insulin resistance when induced by the HF, HFHP diets but that it was under the HFruc diet." (PMID 23298392, 2013). "Hepatic steatosis due to trans-10, cis-12 CLA is also seen in the absence of insulin and is associated with reduced expression of SCD1 and other lipogenic genes." (PMID 21869929, 2012). "As in MTTP deficient mice, the TG levels are low as export does not function they show hepatic steatosis but lack insulin resistance or inflammation." (PMID 22363740, 2012). "No hepatic steatosis or liver enlargement was observed and it was accompanied by maintenance of insulin sensitivity, as particularly indicated by ITT and R-QUICKI, despite the higher HOMA-IR index." (PMID 20180981, 2010). "Moreover, the “PPAR signaling pathway”, a major regulatory hub for lipid synthesis, transport, and insulin sensitivity, may represent a critical mechanism by which FRT4 improves lipid metabolism and alleviates hepatic steatosis." (PMID 40870712, 2025). "Moreover, even after accounting for variables including parity, age, hepatic steatosis, pre-pregnancy BMI, AST, HDL-C, GGT, LDL-C, insulin, ALT, and TC in Model 3, a noticeable connection between the TyG index and incident GDM persisted (OR: 12.923, 95%CI: 3.581–46.632, p = 0.00009)." (PMID 38414896, 2024). "However, surviving mice had no hepatic steatosis but rather fat accumulation at the muscle level, with only mild impairment of glucose tolerance and elevation of glucose and insulin levels only in the fed state, indicating modest insulin resistance." (PMID 38727299, 2024). "Since insulin is a crucial regulator of SREBP-1c, improvements in insulin sensitivity, potentially facilitated by probiotics, could inhibit fatty acid synthesis, offering additional protection against hepatic steatosis." (PMID 39290562, 2024). "On the other hand, deleting UBE4A causes severe defects in animal models such as neuronal developmental defects, insulin resistance and hepatic steatosis, suggesting that UBE4A may not be a suitable treatment target for metabolic disease." (PMID 39643078, 2024). "However, in contrast to our study, at the end of the study, no significant changes were observed in the grade of hepatic steatosis, insulin, liver enzymes, total bilirubin, lipid profile, and blood pressure compared to the control group." (PMID 39135554, 2024). "Therefore, since M4 (yellow) was also correlated with hepatic steatosis, DNL, and BMI z-scores, this may relate to improvements in insulin sensitivity with the diet treatment." (PMID 38668319, 2024). "Also, although lowering body weight, dapagliflozin administered to insulin-resistant overweight/obese individuals for 12 weeks did not improve hepatic steatosis." (PMID 37200978, 2023). "Remarkably, while the glucoregulatory function of the novel adipokine is shared with insulin, ISM1 also neutralizes lipid accumulation in the liver by inhibiting de novo lipogenesis, promoting protein synthesis and preventing hepatic steatosis in a diet-induced fatty liver mouse model." (PMID 36595188, 2023). "More recently, several independent laboratories have shown that hepatocyte-specific deletion of Mboat7 (Mboat7HSKO) worsens hepatic steatosis, inflammation, and fibrosis, but unlike the oligonucleotide-based knockdown, does not impact insulin or glucose homeostasis." (PMID 36806709, 2023). "In addition, hepatic steatosis may promote EDA expression through peroxisome proliferators-activated receptor γ (PPARγ), thereby reducing systemic insulin sensitivity." (PMID 36012178, 2022).
Hepatic steatosis (continued). "HFE homozygosity does not increase the risk for NAFLD and iron accumulation in 65 NASH patients was not related to either overall or liver-related mortality or cirrhosis and there was no improvement in hepatic steatosis or insulin sensitivity following 6 months of phlebotomy." (PMID 36555867, 2022). "This suggests that scEmc10 expression could potentially be regulated by hepatic steatosis, but not hepatic insulin resistance." (PMID 36443308, 2022). "Indeed, other studies have shown that increasing the capacity within this adipose depot correlates with diminished liver steatosis, independent of glucose and insulin tolerance." (PMID 35628485, 2022). "Thus, TRF stabilizes bodyweight without changing food intake, reduces hepatic steatosis, and improves glucose and insulin tolerance." (PMID 33495474, 2021). "Among mouse models of diet-induced obesity (DIO) with hepatocyte-specific knockout of various genes related to insulin signaling, LIrs2KO mice, but not LIrs1KO and LIrs1/2DKO mice, were not protected from hepatic steatosis in spite of the partial impairment of hepatic insulin signaling." (PMID 33923817, 2021). "Liver-specific postnatal knockout of HDAC3 in mice induced an imbalance between carbohydrate and lipid metabolism, with increased insulin sensitivity and reduced glucose production co-occurring with severe hepatic steatosis and a dramatic increase in cholesterol production and de novo lipogenesis." (PMID 34046015, 2021). "Another study showed that the absence of the double bond could restore insulin sensitivity and produce hepatic steatosis in DHCer desaturase 1 knock‐out mice, suggesting an essential role of the double bond on apoptosis and insulin signaling." (PMID 34105193, 2021). "However, in our study, the pharmacological inhibition of TLR4 using eritoran did not improve systemic insulin resistance and hepatic steatosis in the FFD-fed mice." (PMID 34205789, 2021). "Several studies investigating not only BMI but also body fat percentage, fatty liver disease, glucose tolerance and insulin resistance in HF and non-HF patients, found similar correlations and suppose the amount of adipose tissue to be an important contributing factor in decreasing NT-proBNP levels." (PMID 33704552, 2021). "Consequently, hepatic steatosis suggests that excess calories are not efficiently stored in adipose tissue, possibly reflecting adipocyte insulin resistance and inability to expand the fat depots." (PMID 32843711, 2020). "Thus, linagliptin improved OSI-906-induced hepatic steatosis via a pathway that was independent of insulin signaling, glucose levels, or free fatty acid metabolism." (PMID 33105604, 2020). "We observed increases in both Ppara and Pparg mRNA expression in rats regardless of treatment with insulin and/or hCG, and this suggests that the induction of varying degrees of hepatic steatosis by the different treatments depends on the balance between PPARα and PPARβ activity." (PMID 29719598, 2018). "The blood levels of NEFA, insulin, alanine aminotransferase (ALT), aspartate aminotransferase (AST), and total bilirubin (TBIL) were significantly higher, but alkaline phosphatase (ALP) and glucose (GLU) were markedly lower in dairy cows with fatty liver than in healthy cows." (PMID 29882814, 2018). "We show that dysregulation of insulin-mediated IRS–PI3K–Akt signaling pathway results in an imbalance between de novo lipogenesis and mitochondrial β-oxidation, as well as impaired hepatic gluconeogenic pathway, thereby exacerbating fat accumulation and the resultant hepatic steatosis." (PMID 29719598, 2018). "Moreover, patients with NAFLD showed significantly higher values of ALT, AST, and GGT activities, insulin, HOMA-IR, uric acid, ferritin, BMI, waist circumferences, degree of liver steatosis (USG), and total amount of lipids in 1HMRS compared to children without NAFLD." (PMID 29854715, 2018).
Hepatic steatosis (continued). "Collectively, the rapid normalization of glucose tolerance and insulin sensitivity upon dietary switch was largely matched by robust reversal of liver steatosis and whole-body glucose overproduction, though not of the impaired hepatic insulin signaling hyporesponsiveness." (PMID 28360082, 2017). "However, despite mild hepatic steatosis, systemic response to insulin was preserved, unlike in other studies." (PMID 28534852, 2017). "Thus, the development of fatty liver in this study likely occurred through the action of insulin on non-hepatic tissues, but not on the liver." (PMID 28646158, 2017). "Thus, hepatic PPARγ activation is not indispensable for whole-body insulin-sensitizing action but contributes to the side effects of fatty liver in mice." (PMID 28611668, 2017). "One study investigated the effects of ATGL gene manipulation on insulin sensitivity in mice, and here the authors observed that while ATGL knock-out mice do develop marked hepatic steatosis this does not result in any changes to their hepatocyte insulin sensitivity." (PMID 26978356, 2016). "Hepatic ATGL overproduction in the same mice resulted in reduced hepatic steatosis, and interestingly the authors did observe a mild increase in insulin sensitivity although this was not sufficiently large to result in improvements in fasting glucose concentrations or insulinaemia." (PMID 26978356, 2016). "The severity of hepatic steatosis determined by ultrasound positively correlates with visceral fat accumulation and insulin resistance in both obese and non-obese individuals, suggesting that hepatic steatosis is influenced by visceral fat accumulation regardless of obesity." (PMID 24786095, 2014). "However, it is also suggested that hepatic steatosis is secondary to an insulin resistant state due to a lack of insulin dependent suppression of lipid synthesis." (PMID 24520329, 2014). "Interestingly, mice with whole body deficiency of GPx1, a key enzyme in ROS detoxification, fail to become obese mice on a high-fat diet, do not develop hepatic steatosis, and have improved hepatic insulin signalling." (PMID 24672550, 2014). "The improvement of hepatic steatosis and presumably inflammation is likely due to activation of GLP-1R on hepatocytes, because others have shown that exenatide stimulates hepatocyte expression of PPARα and PPARγ that improve hepatic fatty acid oxidation, lipid export, and insulin sensitivity." (PMID 24188631, 2013). "However, the presence of hepatic steatosis argues against this assumption, and unlike insulin signaling related to glucose homeostasis, promotion of lipogenesis by insulin is preserved, driving the synthesis and accumulation of triglyceride in the liver." (PMID 24284392, 2013). "Whether hepatic insulin sensitivity contributes to, or is secondary to reduced hepatic steatosis was not determined in these studies." (PMID 21211044, 2011). "Moreover, adding an Lxr-agonist to healthy mice induced hepatic steatosis while not affecting blood glucose levels, whole-body insulin sensitivity nor metabolic clearance rate]." (PMID 22087215, 2011). "However, these measures did not normalize insulin sensitivity and liver steatosis." (PMID 40842493, 2025). "In addition to its effects on insulin and glucagon, GLP-1 exhibits a wide range of actions, including promoting insulin sensitivity in the adipose tissue, stimulating energy expenditure and fat breakdown, reducing hepatic steatosis and liver lipid content, and delaying gastric emptying." (PMID 39201257, 2024). "Therefore, FOXO3 may have opposite regulatory effects on hepatic steatosis under insulin-dependent and non-independent signaling." (PMID 35222075, 2022). "Microbial therapies could improve liver steatosis, total cholesterol (TC), triglyceride (TG), low-density lipoprotein (LDL-c), alanine aminotransferase (ALT), alkaline phosphatase (ALP), glutamyl transpeptidase (GGT), and homeostasis model assessment-insulin resistance (HOMAI-R) (all P < 0.05)." (PMID 36386939, 2022).
Hepatic steatosis (continued). "Thus, in subjects who are with normal body habitus, those with increased CAP value tend to have worse metabolic profiles and insulin sensitivity, and the biochemical indices and proportion of patients with MetS are similar to those who are overweight and with no hepatic steatosis." (PMID 35173677, 2021). "Interestingly, the robust effect of thiamine on hepatic steatosis was not accompanied by an effect on whole-body or adipose insulin resistance, providing evidence that hepatic steatosis may be targeted directly and independently." (PMID 33608323, 2021). "However, liver steatosis was not altered and insulin sensitivity of whole-body was preserved." (PMID 34943809, 2021). "In conditions of chronic overnutrition, both serum insulin and glucocorticoid levels increase, leading to a change in ANGPTL system homeostasis: chronic overexpression of ANGPTL8 in hepatocytes may determine augmented insulin resistance, lipogenesis, increased VLDL secretion, and liver steatosis." (PMID 33451033, 2021). "However, in this study, linagliptin did not reverse the lipodystrophy induced by OSI-906 administration, implying that linagliptin exerts its effect on OSI-906-induced hepatic steatosis without altering either hepatic insulin signaling or insulin signaling in adipose tissue." (PMID 33105604, 2020). "Consequently, this led to improved insulin sensitivity and absent hepatic steatosis." (PMID 29987474, 2018). "However, in contrast to the dose-dependent inhibitory effects of CO-EtOAc on hepatic steatosis, it seems that higher dose of CO-EtOAc did not provide stronger effects on reverting insulin signaling, and the similar phenomenon can also be observed in the blood glucose lowering effects of CO-EtOAc." (PMID 29036927, 2017). "As described by Choh, one rationale for the pathogenesis of this pattern of fatty liver without CAPD is that it could be secondary to an incorrect technique of insulin delivery to the anterior abdominal wall, thereby inadvertently creating intraperitoneal spillage." (PMID 27998312, 2016). "However, daily exercise effectively treats hepatic steatosis in obese OLETF rats in part by increasing hepatic mitochondrial function and complete fatty acid oxidation, decreasing activation of the lipid synthesis pathway, and improving systemic insulin sensitivity." (PMID 21918718, 2012). "Models were adjusted for age, parity, AST, insulin, LDL, hepatic steatosis, GGT, ALT, and HDL, without adjustment for the stratification variable." (PMID 39962434, 2025). "Groups with fatty liver displayed significantly higher fasting glucose, insulin, C-peptide, and HOMA-IR levels than those without fatty liver (P < 0.01)." (PMID 39439559, 2024). "Lean individuals with hepatic steatosis had lower levels of HOMA-IR, fasting insulin, and high levels of HDL-C compared to those with non-lean steatosis (all p < 0.05)." (PMID 37447183, 2023). "Although it has been suggested that IL‐10 in the liver can inhibit TNFα production and protect against hepatic steatosis during HFD, no improvement in insulin sensitivity has been found." (PMID 36637998, 2023). "Within our cohort of insulin-sensitive, non-obese, normotensive, untreated FCH patients, we found a large number of subjects already affected by liver steatosis, as identified by either US or HSI (75%)." (PMID 35892670, 2022). "The fact that we did not observe hepatic steatosis in SDNme7−/− rats could be explained by opposing actions of decreased Nrep favoring lipid deposition and downregulation of Socs2 and Pparg, both of which were shown to prevent hepatic steatosis in spite of negatively affecting insulin resistance." (PMID 33916973, 2021). "Similar to GDF15, FGF21 reduces the body weight through a non-adipose tissue effect; increases insulin sensitivity, adaptive thermogenesis, and uncoupling protein 1 (UCP1)-independent EE; and reverses hepatic steatosis." (PMID 33718833, 2021).
Hepatic steatosis (continued). "Because of the lack of differences in whole‐body insulin sensitivity and liver steatosis between WT and Park2 KO mice fed RC, we focused on HFD‐fed animals to understand the mechanistic basis for the differences in hepatic insulin sensitivity." (PMID 31724300, 2019). "Weight and food intake was decreased;Food preference was changed to carbohydrate from fat;Plasma non-HDL cholesterol was decreased;Hepatic steatosis was prevented;Energy expenditure was increased;GLP-1 secretion was increased;Insulin sensitivity was improved." (PMID 28943619, 2015). "Our group reported that in patients with HCV chronic hepatitis TNFα genotype modulates the activity of the cytokine pathway, influences insulin sensitivity and the severity of HCV chronic hepatitis, but not liver steatosis." (PMID 23394097, 2013). "Thus, female mice did not gain weight and remained insulin-sensitive with fructose supplementation on BCD, despite developing hepatic steatosis." (PMID 39796558, 2024). "Similarly, in this study we show that the ROSI group, although more insulin-sensitive, exhibits higher liver weight and TG content compared to HFD, whereas PEP2 does not worsen HFD-induced hepatic steatosis." (PMID 36837793, 2023). "From fatty liver to nonalcoholic steatohepatitis (NASH), glucose utilization in muscle deteriorates progressively, and hyperinsulinemia are not secondary to a decrease in hepatic insulin extraction." (PMID 36980862, 2023). "The use of PX-104 improved insulin sensitivity and decreased serum GGT and ALT levels after 4 weeks of treatment without increasing serum cholesterol or alkaline phosphatase; however, there was no change in hepatic steatosis measured by 1H‐MRS and PDFF-MRI." (PMID 32930860, 2021). "We observed that individuals having hepatic steatosis derived from MRI were older, comprised more males, had a higher BMI as well as higher levels of HbA1c, fasting glucose, 2-h glucose, fasting insulin, 2-h insulin, and HOMA-IR compared to those without hepatic steatosis." (PMID 34168217, 2021). "Furthermore, HFD-fed Htr2a LKO mice showed decreased hepatic steatosis as examined by histology, NAS, and hepatic TG concentrations without affecting BW, glucose tolerance, insulin sensitivity, and plasma lipid profiles." (PMID 30446669, 2018). "Interestingly, this increase in liver steatosis in HCD-fed mice occurred despite no changes in body weight or percentage body fat, and did not seem to affect liver insulin sensitivity." (PMID 27992582, 2016). "Hepatic steatosis and dietary triglyceride content induced in a model of obese-simple fatty liver are reduced by DGAT2 antisense oligonucleotides in a manner that does not correlate with changes in body weight, adiposity or insulin sensitivity." (PMID 24786095, 2014). "Hepatic steatosis and the dietary triglyceride contents induced in a model of obese-simple fatty liver are reduced by DGAT2 antisense oligonucleotides in a manner that does not correlate with changes in body weight, adiposity or insulin sensitivity." (PMID 24132155, 2013). "High levels of a constitutively active Foxa2 protein (Foxa2T156A), but not the wild-type protein, can decrease liver steatosis, suggesting that Foxa2 could be a pharmacological target for the treatment of NAFL and for improving liver insulin sensitivity." (PMID 22238690, 2012). "Hepatic insulin resistance represents a paradox in hepatic steatosis since insulin receptor activation of insulin receptor substrate-1 (IRS-1) is active and accounts for increased DNL, yet insulin does not inhibit insulin receptor substrate-2, which controls liver gluconeogenesis." (PMID 20300478, 2009). "However, insulin signaling was not improved in vitro following FGFR4 KO, indicating that improved insulin signaling and Igfbp2 expression in vivo were likely a consequence of improved hepatic steatosis in these mice." (PMID 36586437, 2023).